SCN1A (sodium voltage-gated channel alpha subunit 1)
Description:
Pore-forming subunit of Nav1.1, a voltage-gated sodium (Nav) channel that directly mediates the depolarizing phase of action potentials in excitable membranes. Navs, also called VGSCs (voltage-gated sodium channels) or VDSCs (voltage-dependent sodium channels), operate by switching between closed and open conformations depending on the voltage difference across the membrane. In the open conformation they allow Na(+) ions to selectively pass through the pore, along their electrochemical gradient. The influx of Na(+) ions provokes membrane depolarization, initiating the propagation of electrical signals throughout cells and tissues. By regulating the excitability of neurons, ensures that they respond appropriately to synaptic inputs, maintaining the balance between excitation and inhibition in brain neural circuits (By similarity). Nav1.1 plays a role in controlling the excitability and action potential propagation from somatosensory neurons, thereby contributing to the sensory perception of mechanically-induced pain (By similarity).
Synonyms: NAC1; SCN1; Nav1.1; GEFSP2; HBSCI; SMEI; DEE6; DEE6A; DEE6B; DRVT; EIEE6; FEB3; FEB3A; FHM3
Tractability: Small molecule: an approved drug acts on it; a structure with a bound ligand is known; a high-quality ligand is known; it belongs to a druggable protein family. Antibody: UniProt places it where antibodies can reach, with high confidence; its Gene Ontology location is reachable by antibodies, with high confidence; UniProt predicts a signal peptide or a membrane-spanning region; the Human Protein Atlas places it where antibodies can reach. PROTAC: its protein half-life has been measured; a small molecule that binds it is known.
Target class: Voltage-gated ion channel; Voltage-gated sodium channel; Ion channel
Chemical probes: BI-7150 (high quality)
Safety:
Unwanted effects reported when the protein is acted on. In parentheses: how it was acted on, where the effect was seen, and who reports it.
Increased, predation (inhibition; source: AOP-Wiki)
Increased, amputations (inhibition; source: AOP-Wiki)
Reduced, feeding 1 (inhibition; source: AOP-Wiki)
Reduced, survival (inhibition; source: AOP-Wiki)
Increased Mortality (source: AOP-Wiki)
Gene: Protein-coding gene on chromosome 2 (165,984,641 to 166,182,806, reverse strand). Ensembl gene ENSG00000144285.
Subcellular location: Cell membrane
Subcellular location (Human Protein Atlas): Nucleoplasm; Plasma membrane; Nuclear bodies
Pathways (Reactome):
Developmental Biology: Interaction between L1 and Ankyrins
Muscle contraction: Phase 0 - rapid depolarisation
Gene Ontology:
Molecular function: voltage-gated monoatomic ion channel activity involved in regulation of presynaptic membrane potential; voltage-gated sodium channel activity; monoatomic cation channel activity; monoatomic ion channel activity
Biological process: cardiac muscle cell action potential involved in contraction; membrane depolarization during action potential; detection of mechanical stimulus involved in sensory perception of pain; sodium ion transmembrane transport; sodium ion transport; action potential; monoatomic ion transport; regulation of presynaptic membrane potential; transmembrane transport
Cellular component: plasma membrane; voltage-gated sodium channel complex; Z disc; axon; axon initial segment; intercalated disc; membrane; neuronal cell body; node of Ranvier; sodium channel complex; T-tubule
Genetic constraint (gnomAD): Loss-of-function variants: 9 observed, 159.54 expected, observed/expected ratio (o/e) 0.0564, 90% interval 0.033 to 0.098. The upper end of that interval is the gene's LOEUF score, 0.098, which puts it in group 1 of 6, group 1 being the genes least tolerant of losing a copy. Missense variants: 1,291 observed, 2,289 expected, observed/expected ratio (o/e) 0.56, 90% interval 0.54 to 0.59. Synonymous variants: 705 observed, 796.51 expected, observed/expected ratio (o/e) 0.89, 90% interval 0.83 to 0.94.
Gene-disease validity (ClinGen):
ClinGen rates the evidence that SCN1A causes each of these diseases.
Dravet syndrome (autosomal dominant): Definitive.
generalized epilepsy with febrile seizures plus (autosomal dominant): Definitive. A familial epilepsy syndrome in which family members display a seizure disorder from the generalized epilepsy with febrile seizures plus spectrum which ranges from simple febrile seizures (FS) to the more severe phenotype of myoclonic-astatic epilepsy (MAE) or Dravet syndrome (DS).
genetic developmental and epileptic encephalopathy (autosomal dominant): Definitive. A complex neurodevelopmental disorder characterized by a range of developmental delays and epileptic encephalopathy phenotypes.
familial hemiplegic migraine (autosomal dominant): Moderate. A migraine disorder characterized by individual and family history of aura that includes motor weakness.
Homologues: Orthologues: chimpanzee SCN1A (99% identical), macaque SCN1A (99% identical), rabbit SCN1A (99% identical), rat Scn1a (98% identical), mouse Scn1a (98% identical), pig SCN1A (98% identical), dog SCN1A (98% identical), guinea pig SCN1A (96% identical). Paralogues in human: SCN2A (88% identical), SCN3A (84% identical), SCN9A (76% identical), SCN8A (76% identical), SCN4A (63% identical), SCN5A (63% identical), SCN10A (56% identical), SCN11A (46% identical), SCN7A (44% identical), CACNA1A (25% identical), CACNA1B (24% identical), CACNA1C (24% identical), and 14 more.
Diseases named in the same sentence as SCN1A in open-access papers:
SCN1A is named in the same sentence as 250 diseases in open-access papers, as found by Europe PMC text mining. Sharing a sentence is not in itself a finding about the gene and the disease. The quoted sentences say what the papers report.
epilepsy (519 papers, 2008 to 2026). A brain disorder characterized by episodes of abnormally increased neuronal discharge resulting in transient episodes of sensory or motor neurological dysfunction, or psychic dysfunction. "This is critically exemplified by the pathophysiology of SCN1A‐deficient epilepsies like Dravet syndrome, where the NaV1.1, preferentially enriched in GABAergic interneurons, is already compromised." (PMID 41574686, 2026). "Strategies range from restoration of haploinsufficient genes implicated in monogenic epilepsies, such as SCN1A in Dravet syndrome, to modulation of neuronal excitability through engineered ion channels, neuropeptides, and astrocyte-based approaches." (PMID 41898703, 2026). "Dravet syndrome (DS) is a severe, catastrophic childhood epilepsy predominantly caused by loss-of-function mutations in the SCN1A gene, which encodes the voltage-gated sodium channel Nav1.1." (PMID 42123875, 2026). "Mutations in CACNA1A, ATP1A2, and SCN1A, responsible for familial hemiplegic migraine types 1, 2, and 3 (FHM1, FHM2, and FHM3), are also linked to epilepsy." (PMID 40149800, 2025). "Dravet syndrome (DS) is an early-onset epilepsy caused by loss-of-function mutations in the SCN1A gene, which encodes Nav1.1 channels that preferentially regulate activity of inhibitory neurons early in development." (PMID 40924494, 2025). "aEvidence for these therapies comes from studies of individuals with Dravet syndrome, and there is limited evidence for the use of these therapies in other SCN1A-related epilepsies due to loss of function variants." (PMID 40381056, 2025). "Many SCN1A variants associated with autism spectrum disorder and epilepsy exhibit significant loss-of-function effects." (PMID 39996763, 2025). "Genetic/molecular endophenotypes (11.3%, n = 6) explored modifier genes (e.g., GABRG2, SCN1A), polygenic risk scores, and epigenetic markers relevant to epilepsy risk and treatment response." (PMID 41440071, 2025). "For example, loss-of-function mutations in SCN1A cause Dravet syndrome, a severe childhood epilepsy characterized by drug-resistant seizures and sudden unexpected death in epilepsy (SUDEP)." (PMID 41282053, 2025). "While several rodent models (e.g., Scn1a, Scn2a, and Gabrb3 mutants) represent specific genetic mutations associated with epilepsy, others such as GAERS or WAG/Rij rats display spontaneous spike–wave discharges typical of GGEs." (PMID 41585885, 2025). "Across studies of adults and children with epilepsy undergoing genetic testing, SCN1A is the most ubiquitous epilepsy-associated gene." (PMID 40381056, 2025). "For SCN1A, clear correlations exist between channel expression timing, epilepsy onset, and sudden death risk." (PMID 41151066, 2025). "The SCN1A gene encodes the neuronal sodium channel NaV1.1 and is implicated in a spectrum of seizure disorders ranging from FS and GEFS+ to Dravert syndrome." (PMID 41302954, 2025). "In SCN1A‐associated epilepsy, functional analysis and neuron simulation studies resolved variants of uncertain significance and correlated with aspects of phenotype and medication response." (PMID 39838578, 2025). "Therapeutic response in SCN1A-related epilepsies strongly depends on the functional nature of the causative variant." (PMID 41515912, 2025). "Pathogenic SCN1A variants are among the most common identified etiology for monogenic epilepsy, and are associated with a variety of epilepsy phenotypes, ranging from mild (genetic epilepsy with febrile seizures plus [GEFS+]) to severe (Dravet syndrome)." (PMID 39838578, 2025). "The SCN1A gene has about ~1300 recorded point mutations arising from the coding region, making it a clinically relevant epilepsy gene." (PMID 41007641, 2025). "Dravet syndrome (DS) is a severe and catastrophic form of epilepsy primarily caused by monoallelic loss-of-function mutations in the SCN1A gene." (PMID 40217340, 2025).
epilepsy (continued). "Mutations to the SCN1A gene that encodes Nav1.1 have been implicated in various disease phenotypes, including epilepsy and familial hemiplegic migraine 3 (FHM3)." (PMID 39996763, 2025). "Collaborations between institutes like IMBA and academia fund studies on loss-of-function mutations in SCN1A, a sodium channel gene associated with epilepsy in Dravet syndrome." (PMID 40255860, 2025). "In another example, mutations in SCN1A which encodes a voltage-gated sodium channel (Nav1.1), which is necessary for normal circadian rhythms, and is a risk factor for epilepsy." (PMID 41408339, 2025). "This study of a representative sample of individuals with epilepsy and SCN1A variants demonstrates that genotype and channel function correlate with multiple aspects of the epilepsy phenotype." (PMID 39838578, 2025). "Recently, the gain of function of SCN1A has been linked to early infantile developmental and epileptic encephalopathy (for example, Epilepsy of infancy with migrating focal seizures (EIMFS)) with distinct features, including movement disorders." (PMID 40903466, 2025). "Mild missense mutations in SCN1A are often identified in FS patients, while more severe loss-of-function mutations are associated with severe epilepsies such as Dravet syndrome." (PMID 40529445, 2025). "Dravet Syndrome (DS), a rare genetic encephalopathy characterized by severe drug-resistant epilepsy and progressive neurodevelopmental regression in infancy, is caused by de novo mutations in the SCN1A gene on chromosome 2q24 in over 80% of cases." (PMID 40772259, 2025). "Our results highlight several clinical considerations for medical management of children with epilepsy due to SCN1A variants." (PMID 39838578, 2025). "Distinct causal genes underlie the most common monogenic epilepsies identified in adulthood compared to childhood, although SCN1A is the most commonly implicated gene across both populations." (PMID 40381056, 2025). "For instance, alterations in neurotransmitters such as glutamate and GABA; CSD; and mutations in genes including CACNA1A, ATP1A2, and SCN1A have been shown to be highly correlated with both migraine and epilepsy." (PMID 41404467, 2025). "The proportion of cases with de novo pathogenic variants depends on the phenotype: parents affected with SCN1A seizure disorder, and the proportion of probands with the proband phenotype decreases with increasing severity of the proband phenotype." (PMID 40003892, 2025). "The most well-known epilepsy phenotype associated with SCN1A is Dravet syndrome (OMIM: 607208), but it also causes several other epilepsy syndromes which are associated with various significant comorbidities." (PMID 40565516, 2025). "SCN1A LoF variants primarily affect inhibitory circuits, creating a paradox where LoF mutations produce epilepsy phenotypes similar to GoF variants in excitatory Nav channels, but through reduced inhibition rather than direct hyperexcitation." (PMID 41151066, 2025). "We combined automated patch clamp recording with neurophysiological simulations to discern genotype‐function‐phenotype correlations in a real‐world cohort of children with SCN1A‐associated epilepsy." (PMID 39838578, 2025). "Mutations in the SCN1A gene are a major cause of severe epilepsy in infants, while mutations in KCNQ2 and KCNQ3 genes increase neuronal excitability, affecting seizure frequency and type." (PMID 40520613, 2025). "The p.Arg1596Cys missense variant in the SCN1A gene was initially reported in 2007 in a 6-year-old boy with an epilepsy phenotype within the GEFSP2 spectrum." (PMID 38339022, 2024). "Studies suggest that 70-80% of patients suffering from Dravet syndrome, a severe form of epilepsy, have a mutation in the SCN1A gene." (PMID 39119390, 2024). "Epilepsy-associated SCN1A variants were retrieved from the SCN1A mutation database, the HGMD database, and literature reviews." (PMID 40217529, 2024).
epilepsy (continued). "SCN1A, present in 9.8% of cases, was primarily associated with DS, aligning with prior studies indicating frequencies ranging from 8%–15% in epilepsy cohorts." (PMID 39906551, 2024). "The mother of Patient 5 reported epilepsy between ages 6 and 7 and has transmitted the SCN1A:c.3646G>C variant to her daughter with the onset of complex FS at age 2 during an upper respiratory infection." (PMID 38891831, 2024). "Single-nucleotide polymorphisms (SNPs) within the epilepsy gene SCN1A, a subunit of a voltage-gated sodium channel, were associated with the risk of developing TLE or febrile seizures to varying degrees." (PMID 38927072, 2024). "This yielded the first comprehensive findings on developmental brain alterations and volumetric disparities in regional structures among epilepsy patients harboring an SCN1A gene mutation." (PMID 38383725, 2024). "We review existing studies regarding metabolism in epilepsies caused by mutations in sodium (SCN1A) and potassium (KCNA1) channels." (PMID 37594756, 2024). "For many years now, channelopathies, mainly represented by SCN1A channelopathy, have been considered the prominent cause of epilepsy, a theory that seems to fade with advanced understanding of epileptogenesis." (PMID 38891831, 2024). "The SCN1A gene was first associated with genetic (formerly generalized) epilepsy with febrile seizures plus (GEFSP2/GEFS+)." (PMID 38785537, 2024). "One likely pathogenic EPM2A variant associated with Lafora disease, and one likely pathogenic SCN1A variant associated with DS were identified on the epilepsy panel." (PMID 38756210, 2024). "Scn8a is associated with treatable epilepsy and is a variant of Scn1a, which intensifies trigeminal nociception in Familial Hemiplegic Migraine type 3." (PMID 39390364, 2024). "In the present preliminary report, we performed a case–control study to analyze two potentially functional SNVs of the MIR-146A and SCN1A genes and the risk of epilepsy in a Brazilian cohort sample." (PMID 38892194, 2024). "It focuses on the difficulties faced in diagnostic and treatment strategies for the management of SCN1A-related epilepsy." (PMID 39119390, 2024). "The SCN1A gene, associated with the α-subunit of Nav1.1 channels, has a strong correlation with epilepsy." (PMID 38837984, 2024). "For example, SCN1A gene expression is associated with sudden unexplained death in epilepsy (SUDEP), which has unclear connections to the heart and the brain." (PMID 38766369, 2024). "SCN1A rs3812718 is associated with monotherapy-resistant epilepsy and with maximum doses of ASMs effectiveness in monotherapy." (PMID 39228521, 2024). "In the subset of the patients, genetic testing revealed a specific cellular pathology (e.g., STX1B or SCN1A) as the underlying cause of their epilepsy." (PMID 39137987, 2024). "In humans, mutations in the SCN1A gene causes severe childhood epilepsy, but there are two paralog genes in zebrafish, scn1laa and scn1lab." (PMID 39311118, 2024). "It is crucial to understand genotype–phenotype associations in SCN1A-related epilepsies in order to provide early diagnosis and treatment." (PMID 38785537, 2024). "SCN1A, encoding the NaV1.1 α subunit, is one of the most clinically relevant epilepsy genes, with thousands of genetic variants reported thus far in different phenotypes." (PMID 37654020, 2024). "The overall estimated annual incidence of single-gene epilepsies in this population was 1 per 2120 live births (47.2/100 000; 95% CI 36.9 to 57.5), with pathogenic variants in SCN1A, PCDH19, CDKL5 and KCNQ2, having the highest incidence for DEE." (PMID 39613335, 2024). "SCN1A is one of the most commonly mutated genes associated with epilepsy with a typical autosomal dominant inheritance pattern." (PMID 40217529, 2024). "Variations in SCN1A disrupt sodium channel function, impairing GABAergic inhibitory neurotransmission and leading to hyperexcitability, a hallmark of early-onset epilepsy." (PMID 39906551, 2024).